NF2 (NF2, moesin-ezrin-radixin like (MERLIN) tumor suppressor)
Diseases named in the same sentence as NF2 in open-access papers (continued):
Sharing a sentence is not in itself a finding about the gene and the disease.
glioma (37 papers, 2002 to 2025). A benign or malignant brain and spinal cord tumor that arises from glial cells (astrocytes, oligodendrocytes, ependymal cells). "NF2 gene mutations are noted in several central nervous system tumors, solid-organ tumors, and skin cancers." (PMID 39796693, 2024). "Within the q arm of chromosome 22 are adjacent genes to NF2 that are commonly co-mutated with NF2 in central nervous system tumors." (PMID 39796693, 2024). "NF2 mutations have been implicated, to varying degrees, in several different cancer types, including sporadic central nervous system tumors, solid organ tumors, and tumors of the skin." (PMID 39796693, 2024). "Similar to our findings in Nf2-deficient SC NPCs, ErbB2 increases glioma cell growth by inhibiting apoptosis." (PMID 24817309, 2014). "There is an increasing susceptibility to gliomas in patients with neurofibromatosis type 2 (NF2), the gene for which, NF2, is at 22q12." (PMID 11953826, 2002). "The 29 cases of spinal ependymal tumors investigated by EPICv2-based DNA methylation profiling were additionally subjected to glioma gene panel NGS, in particular to assess their NF2 gene mutation status." (PMID 40137996, 2025). "NF2 is glioma-suppressive, increasing large-tumor suppressor signaling and decreasing canonical and non-canonical Wnt signaling." (PMID 37370851, 2023). "On the other hand, the tumor suppressor NF2, a core molecule governing cell survival, motility, and invasiveness, attenuates the proliferation of glioma cells in the central nervous system." (PMID 32676008, 2020). "Treatment with a VEGF monoclonal antibody has resulted in hearing improvement in patients with NF2-associated VS6, and delivery of siRNA against VEGF or HIF-1α to downregulate VEGF expression reduced glioma growth." (PMID 29018206, 2017). "In conclusion, our results suggest that miRNA-152-3p functions as a novel regulator to promote glioma cells invasion via DNMT1-mediated downregulation of NF2 and can potentially be used as a treatment for GBM." (PMID 28764788, 2017). "Functionally, miR-152-3p overexpression, DNMT1 knockdown and NF2 overexpression significantly induced glioma cell apoptosis and inhibited their invasion." (PMID 28764788, 2017). "Recent work on the tumour suppressor function of NF2 has shown that it is dramatically downregulated in malignant gliomas, resulting in enhanced proliferation of glioma cells, and that it plays a pivotal role in tumorigenesis." (PMID 28764788, 2017). "In these cell lines, we observed that DNMT1 and NF2 were significantly increased and decreased, respectively, in glioma cells compared with HEB cells." (PMID 28764788, 2017). "In our limited analysis of patient derived gliomas, we have detected both nuclear and cytoplasmic interactions among NF2 and T-antigen." (PMID 23308224, 2013). "To explore this possibility, we will investigate if NF2 can aide T-antigen expressing gliomas in regaining control of the cell cycle." (PMID 23308224, 2013). "The pattern of NF2 localization in the human high grade gliomas we examined was predominantly cytoplasmic, though examination of a more extensive set of clinical samples would be informative." (PMID 23308224, 2013). "Imaging-based biomarkers such as perfusion magnetic resonance imaging, already used to assess treatment response in gliomas, could be integrated with molecular readouts (e.g., NF2/hippo status) for multimodal profiling." (PMID 41487565, 2025). "Another non-CNS cancer that has NF2 implications is thyroid cancer." (PMID 39796693, 2024).
glioma (continued). "Furthermore, NEO1 overexpression inhibited the motility of CRC cells (HCT 116) and glioma cells (U251), and this inhibition was partially abolished after silencing NF2." (PMID 36746934, 2023). "Thus, NF2 controls the invasiveness of glioma through YAP-dependent expression of CYR61/CCN1 and miR-296-3p." (PMID 32676008, 2020). "Furthermore, oncogenic YAP1 activation occurs as a consequence of a loss in NF2-dependent inactivation of LATS1 (a key inhibitor of YAP1), and decreased LATS1 activity has also been associated with glioma progression." (PMID 29440180, 2018). "Efficacy results for low-grade glioma, NF2, and other CNS malignancies." (PMID 23641361, 2013). "Indeed, we have observed high levels of NF2 expression in high grade gliomas." (PMID 23308224, 2013). "The mean mRNA and protein levels of NF2 and PTEN were also much higher than those in IDH-wildtype gliomas." (PMID 27852048, 2017). "Methylation of NF2 and DNMT1 was markedly increased, and miR-152-3p was downregulated in GBM tissues and glioma cells." (PMID 28764788, 2017). "Furthermore, PDGF in combination with AdCre;Nf2 gave a higher TTR of 52% (33–71%) with 66% being grade 1, 40% grade 2, and 20% grade 3; however, there was still a high number of gliomas (48%) and a shorter median survival of 189 days." (PMID 37898750, 2023). "Furthermore, NEO1-induced pYAP activation was dramatically attenuated by silencing NF2 in both CRC and Glioma cells." (PMID 36746934, 2023). "In glioma cells, NF2 is phosphorylated and inactivated, which upregulates YAP1 expression and mediates the activation of epidermal growth factor receptor and Notch signalling pathways, promoting glioma cell proliferation and tumour formation." (PMID 37423952, 2023). "In conclusion NF experts and patient representatives consent to prioritise the development of future clinical trials for new drug treatments for MPNST, benign peripheral nerve sheath tumours, cutaneous manifestations and high grade gliomas for NF1; tumour manifestations for NF2; and pain for SWN." (PMID 33903738, 2021).
breast carcinoma (33 papers, 2014 to 2025). "Numerous human and mouse studies have looked at NF2-mutations in breast cancers and have found that these tumors indirectly modulate Hippo signaling when simultaneously mutated with BRCA1 and BARD1." (PMID 39796693, 2024). "The presence of NF2/Merlin mutations in breast cancer has been associated with more aggressive tumor phenotypes and poorer clinical outcomes." (PMID 38136274, 2023). "In an NF2 mutated breast cancer cell line model, YAP, TAZ and TEAD were shown to preferentially localise to enhancer elements." (PMID 35119068, 2022). "We also found that 2% of breast cancer patients harbor NF2 mutations, which specifically occurred in the luminal type and triple-negative breast cancer, and this frequency was higher than that found in the Caucasian population." (PMID 33173047, 2020). "The enhancement of TGF-β signaling was involved in increased reliance of NF2-deficient breast cancer cells on aerobic glycolysis, a metabolic advantage that sustains cell malignancy." (PMID 32299434, 2020). "NF2 has been associated with hereditary neurofibromatosis syndrome 2 and it is mutated at both germinal and somatic levels in breast cancer." (PMID 28569218, 2017). "Mutations in the NF2 gene are rare in breast cancer; instead, Merlin protein levels decrease with disease progression and metastasis due to post-translational degradation." (PMID 28112165, 2017). "Since NF2 mutations activate mTor, we treated a patient with NF2-mutant metaplastic breast cancer (a highly refractory form of breast cancer) with a temsirolimus-based regimen, which resulted in a complete remission." (PMID 24393766, 2014). "As a tumor suppressor gene associated with cancer development, NF2 mutations are also observed in various other human malignancies, including melanoma, clear cell renal cell carcinoma, breast cancer, hepatobiliary cancer, glioblastoma, medullary thyroid carcinoma, and prostate cancer." (PMID 38879686, 2024). "Although low in prevalence, somatic NF2 mutations are also characteristic of some breast cancers." (PMID 39796693, 2024). "Therefore, the role of NF2 mutations is more nuanced in breast cancer, as NF2 loss by way of the Hippo signaling pathway can both contribute to tumorigenesis in some cases but also inhibition of tumor growth in TNBC tumors." (PMID 39796693, 2024). "However, we noticed that NF2-mutated cells were also more sensitive to quinacrine compared to NF2 wildtype mesothelial, lung, ovarian, and breast cancer cells." (PMID 34621176, 2021). "However, in NF2/Merlin-deficient breast cancer cells, reactive oxygen species (ROS) accumulation resulting from decreased levels of anti-oxidant, GSH, lead to elevated Hh signaling." (PMID 32299434, 2020). "Though the evidence for tumour development with NF2 gene variants is sparse except for the nerve sheath tumours, there is now growing evidence that it may be implicated in the development of several other cancers including breast cancer." (PMID 37277882, 2023). "The characteristic malignancy of these breast cancer tissues is thought to be related to the dysregulation of cellular redox management in these NF2 mutant cells." (PMID 39796693, 2024). "Using an NF2 knockout mouse mammary tumor model, a study showed that these NF2-silenced cells had reduced activity of the nuclear factor erythroid 2, like 2 antioxidant transcription factor and increased expression of NADPH oxidases." (PMID 39796693, 2024). "Reduction of NF2 activity also promotes the efficient metastasis of breast cancer and melanoma cells." (PMID 35847022, 2022). "In the NF2-null breast cancer cell line (MDA-MB-231), 70% of the YAP/TAZ/TEAD-occupied enhancers also contained AP-1-binding motifs, making AP-1 the second most abundant motif after TEAD." (PMID 35883668, 2022). "To overcome the challenge of embryonic lethality of a total Nf2‐knockout, we have generated a unique mammary‐specific Nf2‐knockout mouse mammary tumor model." (PMID 33410252, 2021).
breast carcinoma (continued). "In order to recapitulate clinical evidence, we generated a unique, conditional Nf2‐knockout (Nf2−/−) mouse mammary tumor model." (PMID 33410252, 2021). "We used UALCAN and KM-plotter database to study NF2 expression in human breast cancer and corresponding normal tissues and analyzed its relationship with clinicopathological parameters." (PMID 32337368, 2020). "We investigated the role of NF2 in breast cancer cells behavior by inhibiting its expression in MDA-MB-231 and MCF-7 cells." (PMID 32337368, 2020). "In this study, we found that the expression of NF2 in breast cancer tissues was positively correlated with the tumor prognosis." (PMID 32337368, 2020). "In this study, we found that NF2 was downregulated in breast cancer tissues compared to the adjacent normal tissues." (PMID 32337368, 2020). "The findings of the current study reveal that miR-24, miR-141, miR-23a, miR-19a, miR-27a, and miR-15a are involved in the downregulation of NF2 expression in human breast cancer cells." (PMID 30013305, 2018). "Hypermethylation of the LATS1 and LATS2 promoters is observed in 50% of breast cancers, whereas genomic loss of LATS1, LATS2, and NF2 also occurs in TNBC." (PMID 29562176, 2018). "We confirmed that 8 genes—MAPK14, CLOCK, NF2, HMGA2, CXCL12, E2F1, NOTCH1, and CD24—are associated with breast cancer." (PMID 30013305, 2018). "NF2 protein level was found reduced in metastatic breast cancer tissues." (PMID 38755629, 2024). "The cancers described as having non-driver NF2 mutations in this review are breast cancer, hepatocellular carcinoma, and melanoma." (PMID 39796693, 2024). "Distribution of VUS in breast cancer predisposing genes were :APC:1(5.8%), ATM:2(11.7%), BRCA1:1(5.8%), BRCA2:5(29.4%), BRIP1:1(5.8%), CDKN2A:1(5.8%), CHEK2:2(11.7%), FANC1:1(5.8%), MET:1(5.8%), STK11:1(5.8%), NF2:1(5.8%)." (PMID 37277882, 2023). "A VUS was detected in the NF2 gene, in a young breast cancer patient." (PMID 37277882, 2023). "Importantly, mammary‐specific Nf2−/− in an Mouse mammary tumor virus Neu + murine breast cancer model demonstrated accelerated mammary carcinogenesis in vivo." (PMID 33410252, 2021). "In summary, we investigated the role of NF2 in breast cancer cell stemness, proliferation." (PMID 32337368, 2020). "Our results indicate a role of NF2 in the progression of breast cancer." (PMID 32337368, 2020). "We analyzed NF2 mRNA expression in breast cancer tissue by using TCGA database." (PMID 32337368, 2020). "In addition, activation of the Hippo pathway by reconstituting NF2 expression in NF2-null breast cancer cell lines results in a robust LATS1/2-dependent inhibition of YAP/TAZ activity." (PMID 32960816, 2020). "To explore the impact of NF2 on breast cancer cell proliferation, we performed a CCK8 assay." (PMID 32337368, 2020). "Dai et al21 showed that NF2 was a tumor suppressor gene in human breast cancer." (PMID 30013305, 2018). "With further sequence analysis, we found that miR-141, miR-23a, and miR-27a may be involved in the downregulation of NF2 expression in breast cancer cells." (PMID 30013305, 2018). "Finally, the use of OncoScantm has allowed us to detected mutations in five genes that have not been shown to be mutated in TCGA subset of Her-2 overexpressing breast cancer: CTNNB1, HRAS, KRAS, NF2 and SMARCB1." (PMID 28247034, 2017). "NF2 gene is not reported to be a well-established breast cancer predisposing gene." (PMID 37277882, 2023). "Our findings suggest that NF2 may be novel targets for breast cancer therapeutics." (PMID 32337368, 2020). "Our data also evidenced that some YAP/TAZ target genes, such as NF2, AXL, SOX2 and BIRC5, were regulated by Bcl-2 specifically in breast carcinoma model." (PMID 38755629, 2024). "Family history of breast cancer was observed either in first-, second- or third-degree relatives in all patients except in the patients carrying a VUS in the APC, BRIP1 and NF2 genes." (PMID 37277882, 2023).
breast carcinoma (continued). "However, the expression level and function of NF2 in breast cancer remain unclear." (PMID 32337368, 2020). "Compared to FRAX486, IPP-14 induced reduction of viability in two kinds of NF2-impaired cell lines, MDA-MB-231 (human breast cancer cells) and ACHN (human renal cancer cells)." (PMID 28423593, 2017). "More recently, a study looking at NF2 expression in breast cancer cells found that there was relative downregulation of NF2 in breast cancer tissue compared to non-neoplastic adjacent tissue." (PMID 39796693, 2024). "An interesting finding is that though we detected a VUS in the NF2 gene, no previous studies had reported any VUS in this gene in association with breast cancer." (PMID 37277882, 2023). "The expression levels of the upstream molecules in this pathway, such as Kibra, FRMD6/Willin and Merlin/NF2, were upregulated or downregulated at both the transcriptional and protein levels with overexpressing or knocking down N3ICD in MDA-MB-231 breast cancer cells, respectively." (PMID 27841855, 2016). "Therefore, a lack of NF2 ubiquitination in BRCA1- and BARD1-deficient breast cancer cells contributes to tumor formation." (PMID 39796693, 2024).
malignant mesothelioma (29 papers, 2008 to 2025). A malignant neoplasm of the pleura or peritoneum, arising from mesothelial cells. "While genetic alterations in Hippo signaling are rare in human cancer, several pathway components, particularly NF2, are frequently inactivated by somatic mutations in malignant mesothelioma, leading to common YAP/TAZ activation in this rare type of cancer." (PMID 40940864, 2025). "Patients with malignant mesothelioma harboring NF2 mutations respond to TEAD inhibitor; however, the NF2 mutation rate in lung squamous cell carcinoma is only 2.2%." (PMID 38499647, 2024). "Targeted therapeutic trials are underway for malignant mesothelioma in the form of TEAD palmitoylation inhibitors that block the proliferation of NF2-deficient tumors by blocking Hippo signaling gene expression." (PMID 39796693, 2024). "The potential anti-cancer role of TEAD palmitoylation has been demonstrated in NF2-deficient malignant mesothelioma." (PMID 38499647, 2024). "VT3989 has progressed to clinical trials and has shown promising antitumor effects in patients with malignant mesothelioma and other advanced tumors harboring NF2 mutations." (PMID 38067201, 2023). "NF2 is a tumor suppressor gene that predisposes patients to the development of bilateral vestibular schwannomas, spinal schwannomas, meningiomas, and malignant mesothelioma." (PMID 36553016, 2022). "A comprehensive study of 32 different cancers revealed that malignant mesothelioma has the highest frequency of NF2 mutations." (PMID 36523977, 2022). "Loss of function of NF2, which is one of the regulators of the Hippo pathway, is observed in 19–50% of malignant mesotheliomas." (PMID 35916358, 2022). "Around 30% of malignant mesotheliomas have been identified with somatic mutations in NF2." (PMID 39796693, 2024). "Thus, heterozygous NF2+/− mice had a higher sensitivity to asbestos, which resulted in an increased risk of malignant mesothelioma formation compared to wild-type NF2+/+ mice." (PMID 29587439, 2018). "Combined mutations of BAP1, NF2, and CDKN2A are observed in about 34% of malignant mesothelioma, indicating the importance of these tumor suppressors in the disease pathogenesis." (PMID 35204459, 2022). "In malignant mesothelioma, NF2 transcription is usually truncated, and malignant cells cultures show a lack of p16/ARF expression." (PMID 36553016, 2022). "NF2, which is upstream of LATS2 kinase in the Hippo pathway, is another causative gene for malignant mesothelioma." (PMID 36335095, 2022). "Mice exposed to asbestos fibers and inactivating NF2 showed a higher frequency of malignant mesothelioma." (PMID 36553016, 2022). "Specifically, the inhibition of YAP1 activation and the subsequent reduction of already established tumors in vivo clearly demonstrate that YAP1 is a driver of tumor maintenance in malignant mesothelioma with the Hippo pathway or NF2 deletions." (PMID 34685695, 2021). "We have generated mouse models of malignant mesothelioma (MM) based upon disruption of the Bap1, Nf2, and Cdkn2ab tumor suppressor loci in various combinations as also frequently observed in human MM." (PMID 32271879, 2020). "Towards this goal we investigated YAP1 binding in NCI-H2052 malignant mesothelioma cells, a cell line of different lineage and with a different mechanism of YAP1 activation (NF2 mutation, LATS2 deletion)." (PMID 26295846, 2015). "In malignant mesothelioma, NF2/merlin inactivation is observed in approximately 40% of cases, indicating its critical role in cancer development and progression, which is associated with the activation of the Hippo and mTOR signaling pathways involved in cancer progression." (PMID 39712860, 2025). "However, to date, very few cases describing patients diagnosed with both NF2 and malignant mesothelioma have been reported by the literature, and they were all adults." (PMID 40725095, 2025).